LTA4H (leukotriene A4 hydrolase)
Description:
Bifunctional zinc metalloenzyme that comprises both epoxide hydrolase (EH) and aminopeptidase activities. Acts as an epoxide hydrolase to catalyze the conversion of LTA4 to the pro-inflammatory mediator leukotriene B4 (LTB4). Can utilize LTA5 less effectively as a substrate than LTA4, and produce LTB5. Also has aminopeptidase activity, with high affinity for N-terminal arginines of various synthetic tripeptides. In addition to its pro-inflammatory EH activity, may also counteract inflammation by its aminopeptidase activity, which inactivates by cleavage another neutrophil attractant, the tripeptide Pro-Gly-Pro (PGP), a bioactive fragment of collagen generated by the action of matrix metalloproteinase-9 (MMP9) and prolylendopeptidase (PREPL). Involved also in the biosynthesis of resolvin E1 and 18S-resolvin E1 from eicosapentaenoic acid, two lipid mediators that show potent anti-inflammatory and pro-resolving actions.
Tractability: Small molecule: a drug acting on it is in phase 2 or 3 trials; a structure with a bound ligand is known; a high-quality ligand is known; it has a high-quality binding pocket; it belongs to a druggable protein family. Antibody: its Gene Ontology location is reachable by antibodies, with high confidence. PROTAC: ubiquitination databases record sites on it; its protein half-life has been measured; a small molecule that binds it is known.
Target class: Protease; Enzyme; Metallo protease; Metallo protease MAE clan; Metallo protease M1 family
Chemical probes: LYS006 (high quality)
Gene: Protein-coding gene on chromosome 12 (96,000,753 to 96,043,520, reverse strand). Ensembl gene ENSG00000111144.
Subcellular location: Cytoplasm
Subcellular location (Human Protein Atlas): Cytosol; Nucleoplasm
Pathways (Reactome):
Metabolism: Biosynthesis of D-series resolvins; Biosynthesis of E-series 18(R)-resolvins; Biosynthesis of E-series 18(S)-resolvins; Biosynthesis of aspirin-triggered D-series resolvins; Biosynthesis of protectins; Synthesis of Leukotrienes (LT) and Eoxins (EX)
Immune System: Neutrophil degranulation
Gene Ontology:
Molecular function: aminopeptidase activity; epoxide hydrolase activity; leukotriene-A4 hydrolase activity; metalloaminopeptidase activity; protein binding; RNA binding; tripeptide aminopeptidase activity; zinc ion binding; peptidase activity; metallopeptidase activity
Biological process: leukotriene biosynthetic process; peptide catabolic process; leukotriene metabolic process; proteolysis; response to peptide hormone; response to zinc ion; type I pneumocyte differentiation
Cellular component: cytoplasm; cytosol; extracellular exosome; extracellular region; ficolin-1-rich granule lumen; tertiary granule lumen
Genetic constraint (gnomAD): Loss-of-function variants: 20 observed, 35.19 expected, observed/expected ratio (o/e) 0.57, 90% interval 0.4 to 0.83. The upper end of that interval is the gene's LOEUF score, 0.83, which puts it in group 3 of 6, group 1 being the genes least tolerant of losing a copy. Missense variants: 332 observed, 388.34 expected, observed/expected ratio (o/e) 0.85, 90% interval 0.78 to 0.94. Synonymous variants: 127 observed, 141.14 expected, observed/expected ratio (o/e) 0.9, 90% interval 0.78 to 1.04.
Homologues: Orthologues: chimpanzee LTA4H (100% identical), macaque LTA4H (99% identical), rabbit LTA4H (96% identical), dog LTA4H (95% identical), rat Lta4h (93% identical), mouse Lta4h (93% identical), guinea pig LTA4H (93% identical), pig LTA4H (92% identical), tropical clawed frog lta4h (68% identical), zebrafish lta4h (64% identical), Caenorhabditis elegans ltah-1.1 (45% identical), Drosophila melanogaster CG10602 (45% identical). Paralogues in human: RNPEP (37% identical), RNPEPL1 (32% identical), AOPEP (23% identical), TRHDE (20% identical), ENPEP (19% identical), LNPEP (19% identical), LVRN (19% identical), ANPEP (18% identical), ERAP2 (18% identical), ERAP1 (17% identical), NPEPPS (17% identical).
Diseases named in the same sentence as LTA4H in open-access papers:
LTA4H is named in the same sentence as 82 diseases in open-access papers, as found by Europe PMC text mining. Sharing a sentence is not in itself a finding about the gene and the disease. The quoted sentences say what the papers report.
tuberculous meningitis (15 papers, 2014 to 2026). "TT genotype of Leukotriene A4 hydrolase (LTA4H) promoter region rs17525495 polymorphisms are associated with exaggerated immune responses in Tuberculous meningitis (TBM), the most severe form of extrapulmonary tuberculosis (EPTB)." (PMID 36879040, 2023). "Patients who are homozygous for low or high LTA4H expression alleles developed severe TB meningitis with reduced survival, while those heterozygous for intermediate LTA4H expression controlled the infection." (PMID 29875747, 2018). "Genotypes associated with either high or low LTA4H levels were both found to be detrimental in disseminated TB meningitis." (PMID 24973748, 2014). "Importantly, TNF, which has been implicated in the pathogenesis of tuberculosis, including tuberculous meningitis, appears to be dysfunctionally increased both in an LTA4H-independent and -dependent manner." (PMID 33658385, 2021). "This article describes the planned analyses for the LAST ACT clinical trial, in which corticosteroids (or placebo) were given to HIV-negative adults with tuberculous meningitis stratified by their leukotriene A4 hydrolase (LTA4H) genotype." (PMID 39911285, 2024). "This article describes the planned analyses for the primary publication of the results of the LAST ACT clinical trial (NCT03100786): ‘Leukotriene A4 hydrolase Stratified Trial of Adjunctive Corticosteroids for HIV-negative adults with Tuberculous meningitis’." (PMID 39911285, 2024). "In tuberculous meningitis (TBM), a common functional promoter variant (C/T transition) in the gene encoding leukotriene A4 hydrolase (LTA4H), predicts pre-treatment inflammatory phenotype and response to dexamethasone in HIV-uninfected individuals." (PMID 30363837, 2018). "In humans, the genetic status of LTA4H has been shown to be critical for disease outcome in TB meningitis patients." (PMID 29875747, 2018). "In contrast, heterozygous patients with intermediate levels of LTA4H were protected from TB meningitis, a finding that was subsequently modeled in zebrafish." (PMID 24973748, 2014). "However, patients who suffer from tuberculous meningitis can have one of three variations of part of the gene called LTA4H." (PMID 39911285, 2024). "Leukotriene A4 hydrolase (LTA4H) genotypes associate with distinct intracerebral inflammatory phenotypes and may determine corticosteroid response in tuberculous meningitis, with benefit observed in hyperinflammatory TT genotype but uncertain benefit in lower inflammation CC and CT genotypes." (PMID 41540106, 2026). "Additionally, genetic polymorphisms that modulate inflammatory responses in the host, e.g., leukotriene A4 hydrolase expression (LTA4H), tryptophan metabolism, may affect mortality in patients with TB meningitis." (PMID 35085105, 2022).
asthma (14 papers, 2011 to 2025). "In this study we tested the role of the LTA4H regulatory variant rs2660845 and age of asthma onset in response to montelukast in ethnically diverse populations." (PMID 34550981, 2021). "Polymorphisms spanning genes involved in the production of leukotriene B4 (LTB4) e.g. ALOX5AP and LTA4H are associated with asthma susceptibility, suggesting a role for LTB4 in disease." (PMID 23167751, 2012). "We and others have recently provided preliminary evidence that SNPs spanning ALOX5AP and LTA4H are asthma susceptibility markers and determinants of lung function." (PMID 23167751, 2012). "We have recently reported evidence that SNPs spanning ALOX5AP and LTA4H are asthma susceptibility markers." (PMID 22206291, 2011). "We have previously shown evidence that polymorphisms within genes controlling leukotriene B4 (LTB4) production (ALOX5AP and LTA4H) are associated with asthma susceptibility in children." (PMID 22206291, 2011). "Interestingly, there was modest evidence for a role of ALOX5AP and LTA4H SNPs associated with BTS defined asthma severity." (PMID 23167751, 2012). "for the co-occurrence of the A allele with rs17525488 of the leukotriene A4 hydrolase (LTA4H) gene, which was associated with a reduced risk of asthma and lower baseline lung function." (PMID 41390442, 2025). "Leukotriene A4 hydrolase activation and leukotriene B4 production by eosinophils likely contributes to the presence and severity of inflammation in asthma." (PMID 37241840, 2023). "As LTA4H expression and effects have been shown to be different in late-onset and early-onset asthma, it is possible that the results would be significant in a pediatric study." (PMID 34550981, 2021). "The primary KEGG asthma FcεRI signaling pathway includes LTA4H through its function in AA metabolism (KEGG)." (PMID 32185106, 2020). "The study revealed multiple SNPs and haplotypes in LTA4H, TNFα and IL4-Rα genes which constitute risk factors for the development of difficult asthma in children." (PMID 23573270, 2013). "We retrospectively evaluated SNPs spanning ALOX5AP (8 SNPs) and LTA4H (6 SNPs) that encode for proteins involved in LTB4 production and had previously been associated with asthma susceptibility with BTS defined severity (step 1–5)." (PMID 23167751, 2012). "Our study demonstrates that genetic variation in LTA4H, together with timing of asthma onset, may contribute to variability in montelukast response." (PMID 34550981, 2021). "Since early-onset and late-onset asthma present fundamental differences both in the establishment of disease, as well as genetic variation and expression, we chose to analyse the effect of LTA4H rs2660845 SNP in each onset group." (PMID 34550981, 2021). "In conclusion, we have identified multiple SNPs and haplotypes in LTA4H, TNFα and IL4-Rα genes that constitute risk factors for the development of difficult asthma in children and demonstrate combined effects which confer greater risk than that obtained for any SNP individually." (PMID 23573270, 2013). "Further support for a role of LTB4 in asthma is its increase in exhaled breath condensate of affected patients, and the attenuation of allergic airway inflammation and hyperresponsiveness by LTA4H inhibition." (PMID 22235296, 2012). "Relative to other genes, LTA4H has not been thoroughly examined in genetic association studies and the number of investigations analysing the association of polymorphisms in this gene with asthma-related phenotypes is limited." (PMID 23573270, 2013). "Therefore, LTA4H inhibitors, 5-Lipoxygenase Activating Protein inhibitors and Leukotriene-B4 receptor antagonists might represent a potential therapeutic strategy that could modulate key aspects of early-onset asthma." (PMID 34550981, 2021).
asthma (continued). "The five identified target proteins, ESR1, KDR, LTA4H, PDE4D and PPARG, show evidence of involvement in the pathological expression of asthma, with three classified as receptors (ESR1, KDR, PPARG), and two categorized as enzymes (LTA4H, PDE4D) (KEGG, UniProt)." (PMID 32185106, 2020). "Each of the five identified target proteins, ESR1, KDR, LTA4H, PDE4D and PPARG, have established potential to play significant roles involving both the primary and secondary asthma pathways through many signaling cascade pathways." (PMID 32185106, 2020). "Computational molecular docking of DCT compounds identified five proteins (ESR1, KDR, LTA4H, PDE4D and PPARG) mutually targeted by asthma genes and DCT compounds and 155 docking connections associated with cellular pathways involved in the biological mechanisms of asthma." (PMID 32185106, 2020). "Both LTA4H crystal complexes are classified as antagonists of LTA4H, therefore the 38 DCT-compounds that docked with both crystals of LTA4H potentially reduce asthma symptoms such as increased mucous and persistent airway inflammation, through blocking the conversion of LTA4 to LTB4 (PDB; Uniprot)." (PMID 32185106, 2020).
tuberculosis (13 papers, 2010 to 2025). A chronic, recurrent infection caused by the bacterium Mycobacterium tuberculosis. "Model organisms have also played an important role, as exemplified by zebrafish mutants leading to the discovery of human polymorphisms in LTA4H that are associated with tuberculosis (TB) susceptibility and treatment response." (PMID 27442518, 2016). "Previous work by the Ramakrishnan group identified human mutations in the inflammatory response factor LTA4H that affect susceptibility to tuberculosis." (PMID 24973743, 2014). "A human promoter variant that increases LTA4H expression is associated with a similar increase in tuberculosis severity as a low-LTA4H expressing promoter variant." (PMID 23874453, 2013). "For instance, the leukotriene A4 hydrolase (lta4h) gene has been implicated as a susceptibility locus in leprosy and tuberculosis." (PMID 21909445, 2011). "While tuberculosis susceptibility has historically been ascribed to failed inflammation, it is now known that an excess of leukotriene A4 hydrolase (LTA4H), which catalyzes the final step in leukotriene B4 (LTB4) synthesis, produces a hyperinflammatory state and tuberculosis susceptibility." (PMID 23874453, 2013). "lta4h locus polymorphisms have previously been linked to tuberculosis (TB) susceptibility and disease outcome in a Vietnamese dataset, but further studies suggested that those results were poorly reproducible." (PMID 31817174, 2019).
myocardial infarction (7 papers, 2008 to 2022). Gross necrosis of the myocardium, as a result of interruption of the blood supply to the area, as in coronary thrombosis. "Another member of the leukotriene pathway, the LTA4H gene encoding leukotriene A4 hydrolase, confers a moderate risk of myocardial infarction." (PMID 36011386, 2022). "Genetic variation in the genes ALOX5 (arachidonate 5-lipoxygenase), ALOX5AP (arachidonate 5-lipoxygenase-activating protein) and LTA4H (leukotriene A4 hydrolase) has previously been shown to contribute to the risk of MI (myocardial infarction) in Caucasian and African American populations." (PMID 30678701, 2019). "Recently, a variant of the gene encoding LTB4 hydrolase (LTA4H), a protein in the same biological pathway as ALOX5AP has been shown to be associated with risk of myocardial infarction, further strengthening the case for a role of the lipoxygenase pathway on CVD risk." (PMID 20592751, 2010). "A number of markers, such as myeloid-related protein 14 (MRP-14), cyclooxygenase-1 (COX-1), 5-lipoxygenase activating protein (FLAP), leukotriene A4 hydrolase (LTA4H) and myocyte enhancing factor 2A (MEF2A), have been linked to acute coronary syndromes, including myocardial infarction." (PMID 19578513, 2008). "Polymorphisms in two 5-LO pathway genes; 5-lipoxygenase activating protein (ALOX5AP) and leukotriene A4 hydrolase (LTA4H) have shown an association with LTB4 overproduction from ionomycin-stimulated neutrophils and with myocardial infarction (MI) susceptibility." (PMID 23167751, 2012). "Single nucleotide polymorphisms (SNPs) in two 5-LO pathway genes; 5-lipoxygenase activating protein (ALOX5AP) and leukotriene A4 hydrolase (LTA4H) have shown an association with LTB4 overproduction from ionomycin-stimulated neutrophils and with myocardial infarction (MI) susceptibility." (PMID 22206291, 2011).
leprosy (6 papers, 2010 to 2021). Leprosy is a chronic infectious disease affecting primarily the skin and peripheral nervous system. "then undertook a human genetic study, in which they investigated polymorphisms in the LTA4H gene, a human homologue of lta4h, for association with clinical TB and leprosy phenotypes." (PMID 21112816, 2011). "Also, another gene recently identified as associated to leprosy is LTA4H (leukotriene A4 hydrolase), in which SNPs in the gene loci are associated with protection from the multibacillary form of the disease." (PMID 23798993, 2013). "Later studies demonstrated that the LTA4H gene (LTA4H) is associated with pulmonary tuberculosis, PARK2 and PACRG with leprosy, and a mutant form of CCR5 with reduced HIV-1 transmission." (PMID 33801073, 2021).
colon cancer (5 papers, 2011 to 2023). "These proteases have been implicated in several cancers including aminopeptidase N in colon cancer, cystinyl aminopeptidase in renal cancer, and LTA4H in lung and colon adenocarcinomas." (PMID 21991341, 2011). "Recently, we reported that resveratrol can suppress leukotriene A4 hydrolase (LTA4H) activity, which is over-expressed in lung and colon cancer cells." (PMID 22693608, 2012). "The downregulation of activity of LTA4H, and decrease in tumor burden, after sulindac treatment supports studies in which it has been shown to be upregulated in colon cancer." (PMID 21991341, 2011). "We found that the expression of 5-LO, LTA4H, and LTC4S, central enzymes in LT formation, is potently up-regulated when HT-29 and HCT-116 colon cancer cells are grown as MCTS." (PMID 36849252, 2023).
colorectal cancer (5 papers, 2015 to 2023). A primary or metastatic malignant neoplasm that affects the colon or rectum. "Inhibtion of Leucotriene A4 hydrolase (LTA4H) reduces cellular proliferation in colorectal cancer." (PMID 38304289, 2023). "Additionally, bestatin is an inhibitor of leukotriene A4 hydrolase (LTA4H) and has anticancer effects in colorectal cancer." (PMID 38006022, 2023).
Granuloma (5 papers, 2016 to 2022). A compact, organized collection of mature mononuclear phagocytes, which may be but is not necessarily accompanied by accessory features such as necrosis. "Moreover, pro-inflammatory proteins, such as LTA4H, were highly expressed in caseous regions of the granuloma compared with cellular regions and associated with TNF-α expression." (PMID 27822210, 2016). "The enzyme leukotriene A4 hydrolase (LTA4H) was present in abundance in caseous granulomas, less so in cavitary granulomas, and none was present in solid granulomas." (PMID 35386409, 2022). "Spatial studies combining mass spectrometry with confocal microscopy of dissected human tuberculous granulomas show that necrotic tuberculous granulomas are enriched for LTA4H and TNF as compared to nonnecrotic granulomas from the same lung." (PMID 31474371, 2019). "Spatial studies of human tuberculous granulomas find that necrotic tuberculous granulomas are enriched for LTA4H and TNF as compared to nonnecrotic granulomas from the same lung, making it plausible that corticosteroids exert their effects through these determinants." (PMID 33658385, 2021).
Arthritis (3 papers, 2014 to 2017). Inflammation of a joint. "All other reports on sterile inflammatory conditions unanimously described a strong anti-inflammatory effect of LTA4H inhibition in models of neutrophil driven inflammation such as arthritis, colitis, peritonitis and asthma." (PMID 29051536, 2017). "The involvement of compartmentalized and coupled changes of LTB4 and LTA4H in the resistance and development of arthritis in CIA model was demonstrated for the first time." (PMID 24701582, 2014). "In this study, we showed that the correlations between LTB4 and LTA4H have significance on resistance and development of arthritis in CIA model." (PMID 24701582, 2014). "This study aimed to check the involvement of lipid mediator leukotriene (LT) B4 and the activity of LTA4 hydrolase (LTA4H) in the development of arthritis induced in rats by collagen and adjuvant (CIA)." (PMID 24701582, 2014). "This study aimed to check the involvement of LTB4 content and LTA4H activity, measured by HPLC and EIA, on the development of experimental arthritis in rats." (PMID 24701582, 2014).